ACE (angiotensin I converting enzyme)
Diseases named in the same sentence as ACE in open-access papers (continued):
Sharing a sentence is not in itself a finding about the gene and the disease.
retinal vein occlusion (1 paper, 2014). An occlusion of the retinal vein. "Therefore, we aimed to evaluate the association between ACE I/D polymorphism and retinal vein occlusion (RVO)." (PMID 25161389, 2014). "However, one cannot definitely conclude that ACE gene polymorphism is a risk factor for retinal vein occlusion." (PMID 25161389, 2014).
schizoaffective disorder (1 paper, 2015). "Seventy-two patients with SCZ or schizoaffective disorder diagnosis, and 69 healthy controls (HCs) underwent a cognitive battery with parallel collection of peripheral blood samples to measure ACE activity." (PMID 26645626, 2015).
serous adenocarcinoma (1 paper, 2024). An adenocarcinoma that is characterized by the presence of papillary patterns and cellular budding. "A decreased risk among ACE inhibitors users was observed also in subgroups of patients aged 51–65 years, having serous adenocarcinoma and stage I–III at diagnosis." (PMID 38439058, 2024).
Skeletal myopathy (1 paper, 2014). "Future investigations should focus on the contribution of ACE-AngII-AT1 receptor axis in the amelioration in skeletal myopathy." (PMID 24859374, 2014).
skin cutaneous melanoma (1 paper, 2022). "In contrast, the mutation of ACE was negatively correlated with the overall survival of skin cutaneous melanoma patients." (PMID 35513851, 2022).
small vessel stroke (1 paper, 2014). "We aimed at evaluating the contribution of the angiotensin-converting enzyme (ACE) gene insertion/deletion (I/D) polymorphism to the risk of small-vessel stroke in south Indian population." (PMID 24523965, 2014). "Since the role of ACE I/D polymorphisms in the pathogenesis of ischemic stroke due to cerebral SVD is controversial, our aim was to evaluate the association of this polymorphism with small-vessel stroke in south Indian population." (PMID 24523965, 2014).
sterility (1 paper, 2023). "Angiotensin converting enzyme (ACE) is a male sterility-related enzyme." (PMID 36825227, 2023).
stress incontinence (1 paper, 2013). "Stress urinary incontinence has been associated with the use of alpha-blocking agents, which reduce urethral sphincter tone, and with consumption of ACE inhibitors in patients who experience treatment-related cough." (PMID 23758756, 2013). "A number of case reports describe cough-induced stress incontinence upon initiation of an ACE inhibitor, which remits upon discontinuation, and one case series reported a 10% incidence of severe ACE-inhibitor-induced stress incontinence in diabetic post-menopausal women." (PMID 23758756, 2013).
systemic amyloidosis (1 paper, 2013). "We report two patients with RCM, in whom high levels of plasma ACE were present; the final diagnosis in both cases was cardiac amyloidosis as a clinical manifestation of primary systemic amyloidosis associated with the overproduction of immunoglobulin light chains." (PMID 24826302, 2013). "We present two cases of primary systemic amyloidosis, which are cardiac involvement and elevated ACE levels." (PMID 24826302, 2013). "After these findings and the possible pathophysiological explanation, we suggest clinicians to include primary systemic amyloidosis in the differential diagnosis of a suspected infiltrative multiorganic disease, also when increased serum ACE levels are present." (PMID 24826302, 2013). "Nevertheless, no mention about increased ACE levels in extracerebral primary systemic amyloidosis is available." (PMID 24826302, 2013).
testicular tumours (1 paper, 2023). "Furthermore, certain serum markers associated with testicular tumours – LDH (lactate dehydrogenase), AFP (alpha-fetoprotein), HCG (human chorionic gonadotropin), and ACE (angiotensin-converting enzyme) – are evaluated in the laboratory." (PMID 38090555, 2023).
thrombotic disease (1 paper, 2020). The formation of a blood clot in the lumen of a vessel or heart chamber; causes include coagulation disorders and vascular endothelial injury. "An imbalance of ACE-2 and ACE-1 activity at sites of endothelial injury may promote angiotensin II accumulation, which can further exacerbate tissue injury and lead to microvascular thrombotic disease." (PMID 33266474, 2020).
unstable angina pectoris (1 paper, 2013). "Most patients were discharged on aspirin, β-blockers, ACE inhibitors and statins and remained pain free; 23% of cases were re-admitted to hospital during follow up, most commonly with unstable angina pectoris (UAP) (54%, data not shown); 16% of cases underwent subsequent angiography." (PMID 24217040, 2013).
urolithiasis (1 paper, 2025). Stone(s) within the urinary tract. "Naringenin also demonstrated moderate to strong binding affinity with other urolithiasis and renal protection-related targets, including glycolate oxidase (−8.3 kcal/mol), a key enzyme in oxalate synthesis, and ACE (−7.9 kcal/mol), involved in the renin–angiotensin system." (PMID 40573268, 2025).
viral hepatitis (1 paper, 2021). An acute or chronic inflammation of the liver parenchyma caused by viruses. "However, in this study, the seven analyzed articles were not limited to viral hepatitis, and only two articles were analyzed by RCTs; therefore, there is insufficient evidence that ACE inhibitors or ARBs improve fibrosis in viral hepatitis." (PMID 34231046, 2021).
vitamin A deficiency (1 paper, 2019). Deficiency of vitamin A due to malnutrition, malabsorption, or dietary lack. "Environmental factors, such as vitamin A deficiency or exposure to teratogenic substances such as angiotensin-converting enzyme (ACE) inhibitors, among others, can affect proper kidney development." (PMID 30967415, 2019).
white blood cell diseases (1 paper, 2022). "However, in our analyses, ACE inhibitors were found to be protective against white blood cell diseases, immune disorders, and nutritional anemia." (PMID 35689299, 2022).
cardiovascular disease (530 papers, 2004 to 2026). "Elevated ACE expression in tissues (which is generally reflected by blood ACE levels) is associated with an increased risk of cardiovascular diseases." (PMID 38790902, 2024). "Using marine peptides for ACE inhibition not only broadens the repertory of bioactive compounds but also shows promise for tackling the global health burden caused by cardiovascular diseases." (PMID 39452857, 2024). "Neither a recently published prospective study nor retrospective studies found any indication for an increased risk of anaphylaxis in patients with cardiovascular disease or in those using β-blockers or ACE inhibitors." (PMID 38143939, 2023). "These risk variants downregulate ACE2 expression, which affects the ACE inhibitor and bradykinin pathways and increases activities of multiple pathophysiological pathways that contribute to cardiovascular disease." (PMID 36859360, 2023). "Elevated blood ACE is a marker for granulomatous diseases and elevated ACE expression in tissues is associated with increased risk of cardiovascular diseases." (PMID 36831070, 2023). "Typically, β-blockers and ACE inhibitors are used to treat cardiovascular disease, which in turn is a risk factor for more severe anaphylaxis." (PMID 37854067, 2023). "Elevated ACE expression in tissues (reflected by blood ACE levels) is associated with increased risk of cardiovascular diseases and is also a marker for granulomatous diseases." (PMID 35996109, 2022). "As the cornerstones in cardiovascular disease management, ACEis cause inhibition of angiotensin-converting enzyme (ACE, also known as kininase II)." (PMID 36818914, 2022). "The most studied genetic variant of the RAS are polymorphisms of the A1166C AGTR1 and the I/D ACE in the files of cardiovascular diseases." (PMID 35886041, 2022). "ACE2 negatively regulates the RAS via counteracting ACE, an angiotensin-converting enzyme that mediates angiotensin II production to cause cardiovasculare diseases especially hypertension." (PMID 35401827, 2022). "There was also a significant direct positive effect on atherosclerotic cardiovascular disease risk from plasma ACE level (path coefficient = 0.410, p = 0.000)." (PMID 35885904, 2022). "Trial evidence elsewhere has shown that in patients with established ACVD, medicines such as anti‐platelet therapy, ACE inhibitors, beta‐blockers and statins are cost‐effective in reducing the risk of subsequent cardiovascular disease (CVD) events." (PMID 33528881, 2021). "Accordingly, factors affecting circulating ACE activities have been implicated in the pathomechanism of cardiovascular disease." (PMID 34359878, 2021). "Several factors including lipotoxicity, oxidative imbalance, exacerbated ACE activity and altered bioenergetics have been implicated in the pathophysiology of cardiovascular diseases." (PMID 34093172, 2021). "Insertion/deletion (I/D) ACE polymorphism was associated with cardiovascular disease in which the D allele increased risk of cardiovascular disease." (PMID 33712060, 2021). "The ACE gene has become one of the most researched candidate genes for its influence on the risk for hypertension, along with cardiovascular diseases." (PMID 35011591, 2021). "Angiotensin-converting enzyme (ACE) inhibitors are widely used in cardiovascular disease and have been shown to be associated with beneficial effects on EPCs in severalin vitro and clinical studies." (PMID 34707860, 2021). "Several factors including lipotoxicity, oxidative imbalance, exacerbated angiotensin-converting enzyme (ACE) activity and altered bioenergetics have been implicated in the pathophysiology of cardiovascular diseases." (PMID 34093172, 2021). "The ACE rs4646994 polymorphic locus of the angiotensin-converting enzyme gene has been studied for many years, and its association with cardiovascular diseases is well known." (PMID 34065198, 2021).
cardiovascular disease (continued). "Among genetic polymorphisms of ACE, I/D polymorphism has been most extensively studied in several cardiovascular diseases." (PMID 34451921, 2021). "In conclusion, women of ACE DI/II in pre-menopausal stage seem to have lower risk in developing cardiovascular disease than women of ACE DD, and in post-menopausal stage, the risk was similar in women of the two different ACE genotypes." (PMID 33041838, 2020). "We hope the results will help us to know more about the potential risk in developing cardiovascular disease in Chinese women of different ACE gene D/I genotypes at different menopause stages." (PMID 33041838, 2020). "The first studied gene in order to identify the genetic variants associated to a high susceptibility to cardiovascular disease was the gene encoding ACE (angiotensin converting enzyme)." (PMID 31547615, 2019). "Alterations in ACE expression or activity are associated with various pathological phenotypes, particularly cardiovascular diseases." (PMID 31042763, 2019). "After reorganization of ACE I/D polymorphism as a genetic marker for cardiovascular disease, many investigations were done to find such a genetic risk relationship." (PMID 31370787, 2019). "The ACE gene, a major component in renin angiotensin aldosterone system, has been implicated in the pathogenesis of cardiovascular disease and essential hypertension." (PMID 30231548, 2018). "Angiotensin-Converting Enzyme Insertion/Deletion polymorphism (ACE I/D polymorphism) has also be linked to cardiovascular diseases." (PMID 27022914, 2016). "The results of the study of ACE I/D polymorphism and cardiovascular disease inIranian population seem conflicting." (PMID 26735603, 2015). "When compared with 1,906 British controls (free from clinical cardiovascular disease), the I allele was found to be over-represented in cases (p = 0.003), as was the ACE II genotype (proportion 0.48 vs. 0.23 in cases vs. controls, respectively) (OR 2.43)." (PMID 25682119, 2015). "In fact, in clinical practice, ACE inhibitors are well established to be effective for treatment of cardiovascular disease in a broad range of high-risk patients including diabetic patients." (PMID 25471116, 2014). "Various studies have reported a relationship between ACE gene I/D polymorphisms and cardiovascular disorders." (PMID 25984491, 2014). "A large body of literature has established a panel of traditional candidate genes implicated in cardiovascular disease, such as angiotensin-converting enzyme (ACE) and angiotensinogen (AGT)." (PMID 24341666, 2013). "Another study showed that, apart from the circulating levels of ACE, the activity of ACE from the heart was higher for DD carriers, while this phenomenon is associated with a higher incidence of cardiovascular disorders." (PMID 23305118, 2013). "The association between ACE I/D and risk of cardiovascular disease appears to be limited to those who carry the PAI-1 5G allele and suggests a protective effect of the ACE D allele." (PMID 20856803, 2010). "Despite controversy regarding the relationship of ACE I/D variants with cardiovascular diseases, experimental studies agree that the ACE polymorphism affects the plasma ACE concentration and activity, which both increase with the number of D alleles [4,10,11,]." (PMID 38707445, 2024). "In the case of ACE inhibitors and β-blockers, for example, the way in which the results were obtained often makes it impossible to distinguish between a possible effect of the drug itself and effects of the underlying cardiovascular disease being treated." (PMID 37854067, 2023). "Given the high risk for T1D patients to develop cardiovascular diseases, and the established role of impaired insulin and autophagy pathways in these diseases, we proposed to analyze the impact of an ACE inhibitor, Cap on the metabolic impairments in a T1D mouse model." (PMID 38092813, 2023).
cardiovascular disease (continued). "Based on the functional importance of ACE in the regulation of blood pressure and its participation in modulation of risk of cardiovascular disorders, ACE might be involved in the potential bidirectional relation between mental and cardiovascular symptoms." (PMID 35606706, 2022). "The ACE*I allele is associated with a significantly lower level of the vasoconstricting angiotensin II in the blood and, accordingly, with resistance to the development of cardiovascular diseases." (PMID 36362280, 2022). "A study suggested the mutation of ACE is associated with increased cardiac fibrosis, adverse cardiovascular diseases and may cause the failure of anti-AF treatment." (PMID 34859062, 2021). "However, theassociation of ACE I/D polymorphism with cardiovascular diseases israther controversial." (PMID 32638886, 2020). "ACE gene I/D polymorphism was studied frequently in cardiovascular diseases." (PMID 27022914, 2016). "In addition, ACE polymorphisms have been associated with problems such as cardiovascular diseases, diabetic nephropathy, renal failure, pulmonary sarcoidosis, and Alzheimer's disease." (PMID 23469169, 2013). "The results of the present study suggest that aberrations in ACE promoter DNA methylation may be an underlying cause of MD and probably a common pathogenic factor for the bi-directional relationship between MD and cardiovascular disorders." (PMID 22808171, 2012). "Among those with at least one PAI-1 5G allele, there is a significantly lower hazard of cardiovascular disease associated with the presence of each ACE D allele (For PAI-1 4G5G: adjusted HR = 0.74, 95% CI: 0.60–0.92; For PAI-1 5G5G: adjusted HR = 0.49, 95% CI: 0.32–0.75)." (PMID 20856803, 2010). "In addition, the pathophysiology of proliferation, oxidative stress, inflammation, and fibrosis, as well as the onset of pathological diseases such as pulmonary, renal, and cardiovascular diseases, are all linked to the overactivation of the ACE/AngII/AT1R axis." (PMID 36851766, 2023). "Furthermore, these antibodies might be associated with protection against cardiovascular diseases, similar to ACE inhibitors, conferring a lower risk in the O blood group." (PMID 35547235, 2022). "Notably, the highest case/fatality ratio in older adults might be due to the increasing prevalence of frailty and comorbid cardiovascular diseases in advanced age, which is known to be associated with increased ACE/ACE2 ratio." (PMID 33240098, 2020). "Furthermore, D allele of ACE I/D polymorphism has also be linked to cardiovascular diseases." (PMID 27022914, 2016). "Additional intervention trials are necessary to investigate whether treating low grade albuminuria with angiotensin receptor blocker (ARB) or/and angiotensin converting enzyme (ACE) inhibitor therapy can reduce the risk for cardiovascular disease and mortality." (PMID 25742159, 2015). "Substituted imidazoles are present in several drugs for cardiovascular diseases, often as angiotensin-converting enzyme (ACE) inhibitors or calcium channel blockers." (PMID 40970084, 2025). "Various synthetic drugs are available in the market to treat cardiovascular disorders, including angiotensin-converting enzyme (ACE) inhibitors." (PMID 41304806, 2025). "Antioxidant properties are also exhibited by angiotensin-converting enzyme inhibitors (ACE-Is) and angiotensin receptor antagonists (ARBs), which are commonly used in cardiovascular diseases." (PMID 40227238, 2025). "Trials, such as the Heart Protection Study and SOLVD, confirmed significant mortality benefits of statins and ACE inhibitors in cardiovascular disease." (PMID 41465371, 2025). "Calcifediol (an analog of vitamin D3) serum levels are negatively correlated with the incidence of cardiovascular disease, and calcifediol decreases ACE activity." (PMID 40927301, 2025).